FAM20C (FAM20C golgi associated secretory pathway kinase)
Diseases named in the same sentence as FAM20C in open-access papers (continued):
Sharing a sentence is not in itself a finding about the gene and the disease.
breast cancer (11 papers, 2013 to 2026). A primary or metastatic malignant neoplasm involving the breast. "In breast cancer, FAM20C promotes bone metastasis by phosphorylating bone morphogenetic protein 4 and enhancing osteoclastogenesis." (PMID 41399371, 2026). "Database analyses have revealed that FAM20C expression is increased in multiple malignant tumors, including central nervous system tumors, breast cancer (BRC), lung adenocarcinoma, pancreatic tumors, and lymphoma." (PMID 39790934, 2025). "Numerous studies have documented the potential contribution of FAM20C to the growth, invasion, and metastasis of glioma, breast cancer, and other cancers, as well as to the mineralization process of teeth and bone." (PMID 39790934, 2025). "In contrast, expression of FAM20C in breast cancer cells acted as a driver of cell proliferation, tumor growth in vivo, and development of bone metastases in a mouse cardiac injection model." (PMID 36912485, 2023). "In breast cancer models, knockout of FAM20C in human MDA-MB-231 invasive breast cancer cells reduced cell attachment to culture surfaces and resulted in decreased cell migration in “scratch-wounds,” chemotaxis, and Matrigel invasion contexts." (PMID 36912485, 2023). "Complex roles of FAM20C activity in the TME are indicated by a mouse model of breast cancer metastasis to bone, in which deletion of fam20C from myeloid cells promoted osteoclast differentiation and bone resorption through increased osteopontin secretion." (PMID 36912485, 2023). "Reduced expression of BMP4 supressed osteoclastic cell differentiation with regulation of Fam20C in breast cancer." (PMID 37333824, 2023). "In contrast, FAM20C in breast cancer cells promotes bone metastasis by facilitating the phosphorylation and secretion of BMP4, which in turn enhances osteoclastogenesis." (PMID 36825005, 2023). "Recent studies have identified Fam20C as a key gene for the progression of lung adenocarcinoma in the context of hypoxia, and the Fam20C inhibitor, FL-1607 as an inducer for the apoptosis and an inhibitor for the migration of breast cancer cells." (PMID 33942849, 2021). "Another substrate, BMP4, is also involved in breast cancer bone metastasis, in which Fam20C facilitates the growth of human breast cancer MDA-BoM-1833 cells and its bone metastasis through phosphorylation of BMP4 to induce osteoclast differentiation." (PMID 34988120, 2021). "More importantly, Fam20C has also been found to enhance the metastasis of several types of human cancers, such as breast cancer and CRC, indicating that Fam20C may be a promising therapeutic target for the current drug development." (PMID 34988120, 2021). "More recently, some small-molecule inhibitors of Fam20C (e.g., FL-1607 and 3r) have been reported to induce apoptosis as well as to prevent metastasis in breast cancer, which may reveal Fam20C as a druggable target for cancer therapy." (PMID 34988120, 2021). "More importantly, Fam20C has also been found to enhance the metastasis of several types of human cancers, such as breast cancer, indicating that Fam20C may be a promising therapeutic target." (PMID 34988120, 2021). "With respect to cancer progression, only two reports suggest that Fam20C may be a possible therapeutic target for breast cancer (BC) and lung adenocarcinoma (LUAD)." (PMID 33306121, 2021). "Previous studies in liver (HepG2), breast cancer (MDA-MB-231), and osteosarcoma (U-2 OS) cell lines demonstrated that FAM20C is a critical regulator of the phosphosecretome." (PMID 41148235, 2025). "In addition, myeloid Fam20C phosphorylates OPN and decreases its secretion, thereby regulating osteoclast differentiation and decelerating breast cancer bone metastasis in vivo." (PMID 34988120, 2021).
breast cancer (continued). "The FAM20C inhibitor, FL-1607, developed through in silico network analysis, molecular modeling, and molecular dynamics approaches, inhibited proliferation of MDA-MB-468 and MDA-MB-231 human breast cancer cell lines and increased apoptosis and inhibited migration of MDA-MB-468 cells." (PMID 36912485, 2023).
hypophosphatemia (10 papers, 2012 to 2023). Lower than normal levels of phosphates in the circulating blood. "Mutations in PHEX, DMP1, and FAM20C have been reported to be responsible for FGF23-related hypophosphatemia." (PMID 36776964, 2023). "It is likely that a combination of cell differentiation failure and hypophosphatemia resulting from the FGF23 excess led to the skeletal defects in the Fam20c-deficient mice." (PMID 22615579, 2012). "Dmp1-, Phex- and Fam20c-deficient mice shared similarities in osteomalacia, hypophosphatemia and the remarkable elevation of FGF23 in the circulation and skeleton." (PMID 22615579, 2012). "In humans, FAM20C is known to be responsible for Raine syndrome, which is characterized by osteosclerosis and ectopic calcification, and an exome sequencing study has recently revealed the association of mutations in this gene with hypophosphatemia." (PMID 24710520, 2014). "Fam20c-deficient mice exhibit hypophosphatemia associated with the increased levels of Fgf23, and a loss-of-function mutation in the gene has been identified in patients who manifested hypophosphatemia." (PMID 24710520, 2014). "We observed that the cKO mice developed skeletal defects and hypophosphatemia, along with altered levels of DMP1, OPN, bone sialoprotein (BSP) and FGF23 in the Fam20C-deficient bone." (PMID 28620244, 2017). "A recent study reported that FAM20C supresses FGF23 production by enhancing DMP1 expression and that inactivation mutations in FAM20C cause FGF23 related hypophosphatemia by decreasing transcription of DMP1." (PMID 25928877, 2015). "The defects in the mineralized tissues of the Fam20c conditional knockout mice could be the combined results of cell differentiation failure and hypophosphatemia." (PMID 22615579, 2012). "However, mice with high serum levels of FGF23, hypophosphatemia, bone and dentin defects due to FAM20C deficiency are not rescued with DMP1 over-expression." (PMID 34360805, 2021). "In mice, selective FAM20C deficiency in the brain produces a phenotype similar to RS, with intracerebral calcifications, accompanied by microgliosis and astrogliosis, events independent of hypophosphatemia." (PMID 34360805, 2021). "Recent researches have shown that the mineralization induced by human cells is disturbed independently of hypophosphatemia and supported a local role for PHEX, DMP1 or FAM20C in matrix mineralization." (PMID 36717535, 2023). "Ablation of the Fam20c gene in conditional knockout mice affects tooth and bone development by downregulation of SIBLING family of proteins such as DMP1 and DSPP and by increasing FGF23 in serum and promoting phosphate excretion and hypophosphatemia." (PMID 27187611, 2016).
glioma (7 papers, 2021 to 2026). A benign or malignant brain and spinal cord tumor that arises from glial cells (astrocytes, oligodendrocytes, ependymal cells). "Moreover, augmented Fam20C expression was found to be positively correlated with the malignancy of gliomas, which makes the expression of Fam20C a possibly diagnostic marker of malignant gliomas." (PMID 34988120, 2021). "In addition, Fam20C was also overexpressed in five other cancers, such as glioma, meningioma, and kidney cancer, and Fam20C overexpression was associated with higher-grade gliomas." (PMID 34970298, 2021). "A recent study has confirmed that the expression of FAM20C is up-regulated in glioma by long-read RNA sequencing." (PMID 39790934, 2025). "Gene set enrichment analysis has revealed that the mechanisms of glioma progression mediated by FAM20C include cell apoptosis, invasion, and metastasis." (PMID 39790934, 2025). "FAM20C is highly expressed in lower-grade glioma, and its expression is positively correlated with the malignant degree and progression of glioma, while negatively correlated with the prognosis of patients." (PMID 39790934, 2025). "In conclusion, FAM20C can affect glioma progression through many ways and is a promising prognostic marker for glioma." (PMID 39790934, 2025). "FAM20C can promote the invasion of glioma in vitro, and FAM20C antibodies can significantly reduce glioma size in animal experiments." (PMID 39790934, 2025). "FAM20C has been proven to be a marker of glioma invasion and can be used as a new therapeutic target for GBM." (PMID 39403379, 2024). "Our research team recently discovered the role of FAM20C in glioma progression to promote the migration of THP1 cells at low concentrations." (PMID 36825005, 2023). "Our study published in 2020 showed that several types of solid tumors, i.e., breast, cervical, colorectal, esophageal, and pancreatic cancers, and especially glioma, had an elevated FAM20C." (PMID 36825005, 2023). "FN1 is a key substrate interacting with FAM20C and was also reported to promote migration and invasion of glioma cells." (PMID 36825005, 2023). "Data from the Cancer Cell Line Encyclopedia (CCLE) database showed that Fam20C was highly expressed in multiple cancer cell lines, especially glioma." (PMID 34970298, 2021). "This study is the first to demonstrate the roles of FAM20C in glioma invasion in vivo." (PMID 39790934, 2025). "The expression of FAM20C is highest in the GCL_TI of DMG1 with high neuronal content, and higher in the invasive niche than in the tumor core across glioma samples." (PMID 36823172, 2023).
autosomal recessive hypophosphatemic rickets (5 papers, 2019 to 2025). Autosomal recessive hypophosphatemic rickets (ARHR) is a hereditary renal phosphate-wasting disorder characterized by hypophosphatemia, rickets and/or osteomalacia and slow growth. "Autosomal dominant hypophosphatemic rickets is due to FGF23 variants, while autosomal recessive hypophosphatemic rickets is due to biallelic variants in DMP1, ENPP1, FAM20C or SLC34A3." (PMID 40533633, 2025). "The three forms of autosomal recessive hypophosphatemic rickets (ARHR) result from mutations in DMP1 [ARHR1,], ENPP1 [ARHR2,], and FAM20C [ARHR3,], while hypophosphatemic rickets and hyperparathyroidism (HRHPT) is caused by mutations that upregulate KLOTHO expression." (PMID 30808384, 2019).
hypophosphatemic rickets (5 papers, 2012 to 2025). Rickets due to low serum phosphate concentrations, the cause of which can be nutritional or genetic. "The phenotypic profiles of the Fam20c-deficient mice resemble those of hereditary hypophosphatemic rickets in humans and rodents resulting from mutations in molecules affecting the regulation of FGF23." (PMID 22615579, 2012). "The global or specific knockout of FAM20C in mineralized tissues in mice can result in hypophosphatemic rickets, along with elevation of fibroblast growth factor 23 and down-regulation of osteoblast differentiation markers." (PMID 39790934, 2025). "It is suggested that the FAM20C- fibroblast growth factor 23-phosphate pathway and osteoblast differentiation disorder play important roles in the occurrence and development of hypophosphatemic rickets." (PMID 39790934, 2025). "Osteocytes also express PHEX, DMP1, ENPP1, and FAM20C, and inactivating mutations cause FGF23-related hypophosphatemic rickets/osteomalacia." (PMID 36246908, 2022). "Additionally, there are still a pool of patients with hereditary hypophosphatemic rickets whose etiology is unknown, and our discovery that the inactivation of Fam20c in mice results in hypophosphatemic rickets necessitates a consideration of screening FAM20C in such patients." (PMID 22615579, 2012). "Osteocytes express FGF23 and other multiple genes responsible for hereditary hypophosphatemic rickets, which include phosphate-regulating gene homologous to endopeptidase on X chromosome (PHEX), dentin matrix protein 1 (DMP1), and family with sequence similarity 20, member C (FAM20C)." (PMID 36246908, 2022).
osteosclerosis (5 papers, 2012 to 2024). Abnormally high bone density. "Affected individuals show generalized osteosclerosis with periosteal bone formation, implying possible inhibitory roles of FAM20C in osteoanabolism or biomineralization." (PMID 36572689, 2022). "Surprisingly, ERS patients do not suffer from constitutional bone diseases such as osteosclerosis indicating that FAM20A does not participate predominantly in the secretion of FAM20C in the developing bone." (PMID 33425910, 2020). "The Fam20c conditional knockout mice developed hypophosphatemic rickets but not osteosclerosis." (PMID 22615579, 2012).
stomach adenocarcinoma (5 papers, 2021 to 2025). "Elevated levels of FAM20C are indicative of a poor prognosis for patients with bladder urothelial carcinoma or stomach adenocarcinoma." (PMID 39790934, 2025). "FAM20C is widely expressed across various cancers, including bladder urothelial carcinoma, brain lower grade glioma and stomach adenocarcinoma." (PMID 39020437, 2024). "Particularly, FAM20C can significantly promote the lymph node metastasis of stomach adenocarcinoma." (PMID 39790934, 2025). "Studies have indicated that FAM20C might be a biomarker for diverse cancers, including triple-negative breast cancer, lung adenocarcinoma, and stomach adenocarcinoma." (PMID 36134026, 2022).
amelogenesis imperfecta (4 papers, 2016 to 2026). Amelogenesis imperfecta (AI) represents a group of developmental conditions affecting the structure and clinical appearance of the enamel of all or nearly all the teeth in a more or less equal manner, and which may be associated with morphologic or biochemical changes elsewhere in the body. "Nonetheless, the physiological importance of the FAM20A-FAM20C complex is clearly demonstrated by the fact that genetic ablation of FAM20A leads to Amelogenesis Imperfecta, that phenocopy mutations in FAM20C itself." (PMID 41301500, 2025).
bladder urothelial carcinoma (4 papers, 2021 to 2025). "Moreover, the decreased expression of Fam20C was found in BLCA (bladder urothelial carcinoma), BRCA (breast invasive carcinoma), COAD (colon adenocarcinoma), KICH (kidney chromophobe), KIRP (kidney renal papillary cell carcinoma), LIHC, and SKCM (skin cutaneous melanoma)." (PMID 33306121, 2021). "After that, GEPIA and TIMER databases were applied to investigate the relations between Fam20C expression and immune infiltration across different cancer types, especially BLCA (bladder urothelial carcinoma), LGG (brain lower grade glioma), and STAD (stomach adenocarcinoma)." (PMID 33306121, 2021).
glioblastoma (4 papers, 2020 to 2024). The most malignant astrocytic tumor (WHO grade IV). "Among genes whose high expression correlates with decreased survival in glioblastoma, we identified several components of the “matrisome” and associated factors (FAM20C, SEMA3F, ADAMTSL4, ADAMTS14, SERPINA5, and CRELD1)." (PMID 32488114, 2020). "Moreover, the FAM20C expression is positively associated with a poor prognosis in breast, lung, and colorectal cancers, as well as glioblastoma." (PMID 34572536, 2021). "A recent study further revealed that FAM20C mediates the invasive growth of stem-like cells in glioblastoma." (PMID 39216004, 2024). "Inhibition of IGFBP3, another FAM20C substrate and a downstream effector of the YTHDF2-MYC axis in glioblastoma stem cells (GSCs), decreases GSC viability without affecting NSCs and impairs glioblastoma growth in vivo." (PMID 36825005, 2023).
lung adenocarcinoma (4 papers, 2021 to 2025). A carcinoma that arises from the lung and is characterized by the presence of malignant glandular epithelial cells. "Hypoxia in lung adenocarcinoma cells can promote the expression of FAM20C and inhibit the DNA methylation of the FAM20C gene, thus facilitating lung adenocarcinoma progression." (PMID 39790934, 2025). "FAM20C is related to hypoxia in lung adenocarcinoma progression." (PMID 39790934, 2025). "More recently, a genome-wide analysis uncovered that high expression and hypomethylation of Fam20C were correlated with poor prognosis in hypoxia-related lung adenocarcinoma (LUAD), in which hypoxia condition promoted FAM20C gene expression, making Fam20C a potential biomarker of LUAD." (PMID 34988120, 2021).
diabetes (3 papers, 2021 to 2025). "Another study originally revealed the possible regulatory effects of Fam20C on (pro)insulin production and correlative secretory pathway trafficking, establishing connections between Fam20C function and the development of diabetes." (PMID 34988120, 2021). "The negative regulation of the IRE1a signal by the FAM20C–PDI axis is physiologically relevant since the terminal UPR contributes to various diseases, including diabetes, cancer, and neurodegeneration." (PMID 36825005, 2023). "That previous report also lacked molecular insight into how FAM20C promotes diabetes and obesity." (PMID 41148235, 2025). "However, in-depth investigations of therapies targeting Fam20C remain limited, and no studies illuminated its therapeutic effects in heart diseases and diabetes, in which experimental evidence confirmed the important pathogenetic role of Fam20C." (PMID 34988120, 2021).
periodontal disease (3 papers, 2014 to 2024). "The histological findings were consistent with results from the X-ray analyses, further confirming that these Fam20C-deficient mice developed periodontal disease." (PMID 25479552, 2014). "Loss of Fam20C function leads to periodontal disease in mice." (PMID 25479552, 2014). "Therefore, this suggests that phosphorylation by FAM20C may regulate Periostin-mediated cell functions and it is of our particular future interest to investigate the biological role of phosphorylated Periostin and its molecular function in both healthy periodontal tissues and periodontal disease." (PMID 33051588, 2020).
rickets (3 papers, 2012 to 2023). Bone softening and weakening usually caused by deficiency or impaired metabolism of vitamin D. Deficiency of calcium, magnesium, or phosphorus may also cause rickets. "Conditional knockout of fam20c in mice was associated with softened bones resulting in rickets, and in serum, reduced phosphate concentration, and elevated fibroblast growth factor 23, supporting that FAM20C has a major role in osteoblast differentiation." (PMID 36912485, 2023). "While the hypophosphatemic rickets phenotypes of 2.3 kb Col 1a1-Cre;Fam20Cflox/flox mice, to a certain degree, resembled those of the Sox-Cre;Fam20Cflox/flox mice in which Fam20C was inactivated in nearly all the tissues, the general health of the former was better than the later." (PMID 28620244, 2017).
triple-negative breast carcinoma (3 papers, 2021 to 2024). An invasive breast carcinoma which is negative for expression of estrogen receptor (ER), progesterone receptor (PR), and human epidermal growth factor receptor 2 (HER2). "Fam20C protein kinase has a significant promotion effect on the metastasis and invasion of triple-negative breast cancer." (PMID 34970298, 2021).
heart failure (2 papers, 2018 to 2021). Inability of the heart to pump blood at an adequate rate to meet tissue metabolic requirements. "The TAC model, which causes hypertrophy and eventual heart failure, is a more targeted and immediately severe stressor than aging, and can directly test Fam20C’s role in the hypertrophic response." (PMID 30520731, 2018). "Physiologically, mice with Fam20c ablated in cardiomyocytes develop heart failure following either aging or induced pressure overload." (PMID 30520731, 2018). "Fam20C has not been previously demonstrated to phosphorylate SR Ca2+ handling proteins or play a critical role in stress-induced heart failure development." (PMID 30520731, 2018).